ZYX (zyxin)
Diseases named in the same sentence as ZYX in open-access papers (continued):
Sharing a sentence is not in itself a finding about the gene and the disease.
keloid (3 papers, 2023 to 2025). An irregularly shaped, elevated mark on the skin caused by deposits of excessive amounts of collagen during wound healing. "In human keloid xenograft nude mouse model, we found that the weight of keloid tissue in the Zyxin siRNA group was 0.021 ± 0.003g, which is significantly decreased than the PBS control group (0.038 ± 0.003g, P < 0.05)." (PMID 37215989, 2023). "In particular, the IHC staining also showed more Zyxin-positive cells in the dermis of SSc, keloid, and LS patients than in normal controls." (PMID 37215989, 2023). "Meanwhile, the protein levels of Zyxin and collagen I were also elevated in the skin tissues of SSc and keloid patients." (PMID 37215989, 2023). "We reported the up-regulation of Zyxin in the fibroblasts of lesional skins from patients with fibrotic diseases and demonstrated antifibrotic effects of Zyxin on in vivo Zyxin knockdown and knockout mice, keloid xenograft mouse model, as well as ex vivo keloid skin explants." (PMID 37215989, 2023). "To better recapitalize the pathogenesis of other skin fibrotic diseases, like keloid, we constructed a keloid nude mouse model and skin explant model, and found that Zyxin inhibition could alleviate skin fibrosis of keloid." (PMID 37215989, 2023). "Therefore, we used the keloid skin explants and interfered Zyxin with siRNA subcutaneously injection." (PMID 37215989, 2023). "Herein, our study found the increased expression of Zyxin in fibrotic diseases' lesion skins, identified the role of Zyxin in skin fibrosis using in vivo models and keloid skin explants, and revealed the molecular mechanism of Zyxin in skin fibrosis through in vitro studies." (PMID 37215989, 2023). "We determined the expression of Zyxin in the skin tissues from SSc (n = 19) and keloid (n = 21) patients and normal samples (n = 21) and found a significant up-regulation of Zyxin in both SSc (2.32 ± 0.24 vs 1.11 ± 0.11, P < 0.01) and keloid patients (2.58 ± 0.32 vs 1.10 ± 0.12, P < 0.01)." (PMID 37215989, 2023). "We found that the focal adhesion pathway was up-regulated and Zyxin appeared to be the primary focal adhesion protein involved in skin fibrosis, and we further verified its expression in Chinese skin tissues of several fibrotic diseases, including SSc, keloid, and LS." (PMID 37215989, 2023). "Moreover, we found Zyxin inhibition could significantly alleviate skin fibrosis using Zyxin knock-down and knock-out mice, nude mouse model and skin explants of human keloid." (PMID 37215989, 2023). "As revealed by western blotting, the protein levels of Zyxin and α-SMA were significantly downregulated after interfering Zyxin in keloid skin explants." (PMID 37215989, 2023). "By identifying shared nodes, including Zyxin and YAP, future antifibrotic strategies may exploit multipathway inhibition to disrupt the synergistic signaling networks sustaining keloid and HTS formation." (PMID 41049267, 2025).
lung carcinoma (3 papers, 2019 to 2022). "Since lung cancer is one of the most frequently diagnosed carcinomas, the aim of our study was to determine the localization and expression levels of ZYX in NSCLC and to correlate the results with the clinicopathological data." (PMID 35740950, 2022). "Along with overexpression of integrin α5 and β1, we also observed an increase in zyxin (ZYX) that is known to regulate motility in lung cancer via integrin α5β1 pathway." (PMID 31827134, 2019). "This may indirectly suggest that ZYX may inhibit the epithelial-mesenchymal transition (EMT) of lung cancer cells." (PMID 35740950, 2022). "The same authors also presented decreased ZYX levels in a mouse model of lung cancer." (PMID 35740950, 2022). "ZYX may also regulate EMT during lung cancer development and may regulate cell–cell adhesion, integrin α5β1 expression, and ECM adhesion." (PMID 31108958, 2019). "However, there are only a few studies on the involvement of ZYX in lung cancer progression." (PMID 35740950, 2022).
psoriasis (3 papers, 2023 to 2026). An autoimmune condition characterized by red, well-delineated plaques with silvery scales that are usually on the extensor surfaces and scalp. "Inflammatory diseases such as psoriasis, inflammatory bowel disease are associated with the expression and regulation of zyxin." (PMID 38712343, 2024). "Verification by ELISA revealed that caldesmon (CALD1), myeloid cell nuclear differentiation antigen (MNDA), and zyxin (ZYX) levels were significantly increased in the psoriasis group with CVD risk factors." (PMID 36804462, 2023). "Elevated zyxin levels in psoriasis may instead reflect shared underlying mechanisms, including chronic inflammation, enhanced cellular migration, and altered mechanotransduction." (PMID 41596291, 2026). "Therefore, although zyxin levels are elevated in certain cancers, a direct link between increased zyxin levels in psoriasis and cancer risk cannot currently be established." (PMID 41596291, 2026). "As cardiovascular disease has been associated with increased zyxin concentrations, this imbalance may have acted as a confounding factor, and the observed differences cannot be attributed solely to psoriasis." (PMID 41596291, 2026). "As psoriasis is treated as a generalized inflammation disorder with a higher cardiovascular risk, evaluating serum zyxin levels may offer insight into shared pathogenic mechanisms and their potential role as biomarkers of systemic involvement." (PMID 41596291, 2026). "Future investigations with larger, well-matched cohorts are required in order to validate these results and to clarify whether zyxin may serve as a biomarker of cardiovascular risk in patients with psoriasis." (PMID 41596291, 2026). "Based on our findings and the current level of knowledge, the precise function of zyxin in the aetiology of psoriasis, and its potential association with components of metabolic syndrome, remains unclear." (PMID 41596291, 2026). "Moreover, we examined the associations between serum zyxin levels and disease severity assessed by the Psoriasis Area and Severity Index (PASI) score, as well as with selected biochemical, inflammatory, and clinical parameters." (PMID 41596291, 2026). "In this study, we evaluated serum zyxin levels in patients with psoriasis and compared them with those of healthy controls." (PMID 41596291, 2026). "A tendency toward higher zyxin levels with increasing age was observed in patients with psoriasis (zyxin and age, r = 0.39; p = 0.058)." (PMID 41596291, 2026). "In our study, we demonstrated only a statistically significant increase in zyxin amounts in the serum of patients with psoriasis in comparison to the controls." (PMID 41596291, 2026). "Our results revealed that serum zyxin amounts were significantly higher in patients with psoriasis compared with the controls." (PMID 41596291, 2026). "One interesting, yet not yet fully assessed, protein involved in the pathogenesis of psoriasis is zyxin." (PMID 41596291, 2026). "Our results demonstrate significantly higher serum zyxin levels in patients with psoriasis compared with controls." (PMID 41596291, 2026). "The goal of this research was to elucidate the function of zyxin in the pathogenesis, development, and progression of psoriasis." (PMID 41596291, 2026). "A weak positive correlation was also noted between zyxin levels and BMI in the psoriasis group (r = 0.14; p = 0.8325)." (PMID 41596291, 2026). "Psoriasis, a chronic inflammatory skin disease, exhibits increased zyxin levels in patients’ plasma." (PMID 38712343, 2024). "Through TMT as one of isobaric labeling tags-based quantitative proteomic analysis and subsequent verification using ELISA, we especially identified three novel biomarkers associated with CVD risks in patients with psoriasis; CALD1, ZYX, and MNDA." (PMID 36804462, 2023). "At the same time, the elevated zyxin levels observed in the psoriasis group may reflect the increased burden of cardiovascular risk factors commonly present in these patients." (PMID 41596291, 2026).
psoriasis (continued). "Furthermore, we investigated potential correlations between zyxin levels and various metabolic parameters in the serum of patients suffering from psoriasis, as well as correlations with psoriasis severity, in comparison to healthy individuals." (PMID 41596291, 2026). "Additionally, we assessed the relationship between serum zyxin levels and both laboratory parameters and clinical features in patients with psoriasis." (PMID 41596291, 2026). "So far, there are limited data on the function of zyxin in the pathogenesis of psoriasis." (PMID 41596291, 2026). "So far, there are limited published articles on the role of zyxin in the pathogenesis of psoriasis." (PMID 41596291, 2026). "Although the observed trends suggest a possible association between zyxin levels and psoriasis, as well as its related comorbidities, none of the correlations analyzed statistical significance and should therefore be interpreted with caution." (PMID 41596291, 2026). "In this context, elevated zyxin levels may reflect an increased burden of age-related comorbidities rather than an age-dependent risk of psoriasis onset itself." (PMID 41596291, 2026). "Nevertheless, the precise role of zyxin in the aetiology of psoriasis remains unclear." (PMID 41596291, 2026). "Therefore, zyxin should currently be regarded as a potential marker of psoriasis-associated systemic alterations rather than a direct indicator of disease activity." (PMID 41596291, 2026). "In this study, we found that differences in the expression of CALD1, ZYX, and MNDA between psoriasis with cardiovascular risk factors and those without cardiovascular risk factors were significant." (PMID 36804462, 2023). "Three novel candidates (MNDA, ZYX, and CALD1) could be potential biomarkers for predicting CVD risks in psoriasis patients." (PMID 36804462, 2023). "However, the lack of a significant correlation with psoriasis severity (PASI score), inflammatory markers, or metabolic parameters indicates that the precise role of zyxin in psoriasis remains unclear." (PMID 41596291, 2026).
viral infection (3 papers, 2015 to 2025). "Zyxin is implicated in cancer progression, morphogenetic cell movements, gene expression, and pattern formation during embryogenesis (21, –, 23), and recently was implicated as a protective factor against viral infection." (PMID 41277845, 2025). "Other than transcription factors and histones, we also found that some proteins, such as zyxin and NALP4, whose functions are unclear in virus infections, were affected by the motif 29-DEMI-32 and/or 39-KEALSDGI-46." (PMID 29207503, 2017).
acute lymphoblastic leukemia (2 papers, 2012 to 2019). Leukemia with an acute onset, characterized by the presence of lymphoblasts in the bone marrow and the peripheral blood. "X95735 (Zyxin) was found to play an important role in differentiating acute myelogenous leukemia (AML) and acute lymphoblastic leukemia (ALL) by multiple authors." (PMID 23148517, 2012).
cognitive decline (2 papers, 2021 to 2025). "Collectively, we propose that C7 and ZYX might be two novel neuron-derived exosomal protein markers, expression of which might be used to evaluate cognitive decline before a clinical diagnosis of AD is warranted." (PMID 34512304, 2021). "Hence, in the current study, for the first time, we demonstrate that C7 (at protein level) and ZYX (in human sample) might be novel neuron-derived protein markers for cognitive decline." (PMID 34512304, 2021).
fibrosis (2 papers, 2022 to 2023). the formation of excess fibrous connective tissue in an organ or tissue in a reparative or reactive process. "In conclusion, our findings support the extension of the targeting of the FAK/PI3K/AKT and TGF-β signaling pathways as an anti-fibrotic strategy in fibrosis skin, and Zyxin appears to be a potent therapeutic target against skin fibrosis." (PMID 37215989, 2023). "Our observations indicate that increased cardiac fibrosis leads to myocardial stiffening in hypertensive zyxin KO mice." (PMID 35075545, 2022).
gastric cancer (2 papers, 2021 to 2023). A primary or metastatic malignant neoplasm involving the stomach. "We also analyzed the correlation of zyxin expression with clinical features and prognosis of gastric cancer patients through the UALCAN database." (PMID 37667739, 2023). "Zyxin reduces gastric cancer cell stemness and EMT by inhibiting the acetylation level of histone H3 K9 and K23, resulting in the downregulation of SNAI1/2." (PMID 37667739, 2023). "To determine the role of zyxin in gastric cancer, we performed a Western blot (WB) analysis of the expression of zyxin in 73 pairs of gastric cancer and adjacent tissue samples from patients with stage I‐IV of this neoplasm." (PMID 37667739, 2023). "We showed that the relative expression levels of zyxin in gastric cancer tissues (cancer tissues/adjacent tissues) were significantly downregulated in advanced clinical stages." (PMID 37667739, 2023). "Relationship between zyxin protein expression and clinical characteristics in the gastric cancer patients." (PMID 37667739, 2023). "To determine the role of zyxin in gastric cancer, we employed three different gastric cancer cell lines: MKN45, N87, and AGS, which differ in their ability to form tumors in vivo." (PMID 37667739, 2023). "In this study, correlations between clinical characteristics and zyxin protein expression in gastric cancer patients were analyzed." (PMID 37667739, 2023). "The results showed that EMT‐promoting factors SNAI1 and SNAI2 were significantly downregulated, while EMT repressors GRHL2 and OVOL1 were significantly upregulated, suggesting that zyxin negatively regulates EMT in gastric cancer cells." (PMID 37667739, 2023). "This study demonstrated that zyxin negatively regulates the progression of gastric cancer by inhibiting the stemness of cancer stem cells and EMT." (PMID 37667739, 2023). "In this study, we found that the expression of zyxin is negatively correlated with the progression of gastric cancer." (PMID 37667739, 2023). "These plots suggest Zyxin, LPP, LIMD1, TRIP6, and FBLIM display high levels of mutational frequency in stomach cancer." (PMID 33808029, 2021). "This experiment demonstrated that zyxin inhibits metastasis of gastric cancer." (PMID 37667739, 2023). "However, the expression of zyxin is inversely correlated to the degree of malignancy of gastric cancer cells, suggesting a potential inhibitory effect of zyxin on tumorigenesis." (PMID 37667739, 2023). "Our data show that the relative expression of zyxin (cancer tissue/noncancerous tissue) is significantly decreased in advanced gastric cancer tissues, suggesting that zyxin may play a negative regulatory role in the progression of gastric cancer." (PMID 37667739, 2023). "Our WB results show that zyxin is downregulated in advanced gastric cancer tissues." (PMID 37667739, 2023). "The specific mechanisms by which zyxin regulates the expression of gastric cancer cell stemness marker CD44 remain unknown." (PMID 37667739, 2023). "Overexpression of zyxin inhibited the stemness and epithelial–mesenchymal transition (EMT) processes in gastric cancer cells." (PMID 37667739, 2023). "In conclusion, this study demonstrated a negative relationship between zyxin expression and the development of gastric cancer." (PMID 37667739, 2023). "Through Co‐IP experiments, we found that zyxin and SIRT1 can physically bind in gastric cancer cells MKN45, which indicates that zyxin may inhibit the initiation and development of gastric cancer through SIRT1." (PMID 37667739, 2023). "The results of this study show that zyxin can inhibit the stemness and EMT of gastric cancer cells." (PMID 37667739, 2023). "In the present study, we show that zyxin upregulates SIRT1, which inhibit EMT in gastric cancer." (PMID 37667739, 2023). "In the present study, the expression levels of zyxin protein in cancer tissues and adjacent noncancerous tissues from 73 gastric cancer patients with different clinical stages were analyzed by Western blot." (PMID 37667739, 2023).
gastric cancer (continued). "We found that the expression of zyxin in gastric cancer is not related to the patient's age, gender, and nodal metastasis status." (PMID 37667739, 2023).
lymph node metastasis (2 papers, 2016 to 2026). "Moreover, increased zyxin expression has been associated with advanced histological-stage and lymph node metastasis, suggesting a potential role in tumour progression and as a prognostic marker." (PMID 41596291, 2026). "Analysis of the relationship between Zyxin immunostaining and clinicopathological parameters showed that higher immunostaining intensity was significantly correlated with histological stage and lymph node metastasis, but not significantly correlated with age or tumour size." (PMID 27030211, 2016).
Macrothrombocytopenia (2 papers, 2021 to 2024). "Research using zyxin-deficient mouse models has revealed severe macrothrombocytopenia resulting from zyxin deficiency." (PMID 38712343, 2024). "Differential proteomic analysis of proteins associated with macrothrombocytopenia revealed that glycoprotein (GP) Ib-IX was significantly reduced in zyxin-deficient platelets." (PMID 34657146, 2021). "To investigate the mechanism for zyxin deficiency-mediated macrothrombocytopenia, we first characterized the megakaryopoiesis in Zyx−/− mice." (PMID 34657146, 2021). "Thus, our data support that zyxin deficiency alters the actin cytoskeleton and microtubular system resulting in defective proplatelet formation and macrothrombocytopenia." (PMID 34657146, 2021). "In the present study, we show that zyxin-deficient mice (Zyx−/−) display macrothrombocytopenia." (PMID 34657146, 2021). "We recently demonstrated that zyxin interacts with NMMHC-IIA, whose coding gene MYH9 has the most macrothrombocytopenia-causing mutations." (PMID 34657146, 2021). "In conclusion, our study demonstrates that zyxin ablation results in macrothrombocytopenia in mice." (PMID 34657146, 2021). "Here we show that zyxin ablation results in profound macrothrombocytopenia." (PMID 34657146, 2021). "In this sense, the current study not only identifies the role of zyxin in the pathogenesis of macrothrombocytopenia, more importantly, but also suggests that defect of zyxin or other cytoskeleton proteins may have the potential to incur macrothrombocytopenia in humans as well." (PMID 34657146, 2021). "Thus, zyxin regulates platelet biogenesis and GPIb-IX surface expression through VASP-mediated cytoskeleton reorganization, uncovering potential mechanisms of macrothrombocytopenia." (PMID 38712343, 2024). "Taken together, our findings identify zyxin as a regulator of platelet biogenesis and GPIb-IX surface expression through VASP-mediated cytoskeleton reorganization, suggesting possible pathogenesis of macrothrombocytopenia." (PMID 34657146, 2021). "In line with the reported macrothrombocytopenia, we found that the absence of zyxin resulted in actin cytoskeleton disorganization and enhanced tubulin filaments in the marginal band." (PMID 34657146, 2021). "Here we show that the absence of zyxin incurs macrothrombocytopenia." (PMID 34657146, 2021).